ZNF692 (zinc finger protein 692)
Diseases named in the same sentence as ZNF692 in open-access papers (continued):
Sharing a sentence is not in itself a finding about the gene and the disease.
cancer (8 papers, 2021 to 2025). A tumor composed of atypical neoplastic, often pleomorphic cells that invade other tissues. "Previous studies have shown abnormal ZNF692 expression in many types of malignancies, and it has been linked to patients’ clinical prognosis and the aggressive characteristics of cancer cells." (PMID 38650011, 2024). "In ccRCC, the expression of ZNF692 was significantly higher in tumor tissue than in adjacent normal tissue, and the expression of this gene was associated with more advanced cancer stage and poor prognosis." (PMID 38735008, 2024). "ZNF692 was implicated in various biological processes, cellular components, and molecular functions within the context of pan cancer." (PMID 37980166, 2023). "The expression of ZNF692 exhibited a significant association with microsatellite instability (MSI) in eight types of cancer and tumor mutational burden (TMB) in ten types of cancer." (PMID 37980166, 2023). "ZNF692 holds potential as a valuable diagnostic, prognostic, and therapeutic target in the context of pan cancer." (PMID 37980166, 2023). "Further, ZNF692's association with cancer stem cells suggests that it may play an important role in tumor recurrence and treatment resistance." (PMID 38291502, 2024). "Subsequently, we examined the prognostic and diagnostic value of ZNF692 expression in pan cancer." (PMID 37980166, 2023). "Consequently, we investigated the association between ZNF692 expression and immune infiltration as well as immune checkpoint expression across various types of cancer." (PMID 37980166, 2023). "To further explore and confirm the role of ZNF692 in ccRCC, we collected 58 pairs of cancer and paracancer samples from ccRCC patients (the patient information is listed in Table SI) and performed IHC analysis using an anti-ZNF692 antibody." (PMID 38735008, 2024). "In terms of cancer aggressiveness and ability to migrate, ZNF692 appears to work by influencing a process known as EMT." (PMID 38291502, 2024). "ZNF692 remained upregulated across discrete cancer stages, with stage 2, 3, and 4 tissues having higher levels of ZNF692 transcripts than stage 1 and normal tissues." (PMID 38735008, 2024). "Firstly, we conducted a preliminary investigation into the clinical significance of ZNF692 in pan cancer, necessitating further validation through a larger sample size in future studies." (PMID 37980166, 2023). "The high expression of ZNF692 in several cancer types, including ACC, CESC, KIRC, LIHC, PRAD, READ, and UCEC, was indicative of poor PFS." (PMID 37980166, 2023). "Our findings indicate a correlation between ZNF692 expression in pan cancer and the infiltration of CAF, as well as the expression of eight immune checkpoint genes." (PMID 37980166, 2023). "Our findings revealed aberrant expression of ZNF692 across various types of cancer, which aligns with previously reported data." (PMID 37980166, 2023). "In this study, we employed bioinformatics analysis and experimental validation to investigate the role of ZNF692 in pan cancer." (PMID 37980166, 2023). "Through the utilization of the cBioPortal database, we have determined that amplification is the prevailing alteration of ZNF692 in pan cancer." (PMID 37980166, 2023). "This investigation sheds light on the diverse functions of ZNF692 in pan cancer and presents a compelling justification for considering ZNF692 as an innovative therapeutic strategy." (PMID 37980166, 2023). "Secondly, we conducted a preliminary exploration of the potential regulatory network of ZNF692 in pan cancer, which required verification through additional experiments in the future." (PMID 37980166, 2023). "By promoting EMT and possibly affecting cancer stem cell-related signaling pathways, ZNF692 may help maintain these cell populations with high malignant potential." (PMID 38291502, 2024).
cancer (continued). "ZNF692 may influence the lineage of cytokines and chemokines secreted by cancer cells, thereby affecting immune cell recruitment, extracellular matrix remodeling, and the behavior of neighboring cells." (PMID 38291502, 2024). "Our findings revealed aberrant expression of ZNF692 across various types of cancer." (PMID 37980166, 2023). "Aberrant expression of ZNF692 was observed across various types of cancer." (PMID 37980166, 2023). "Amplification of ZNF692 emerged as the most frequent alteration in pan cancer." (PMID 37980166, 2023). "Nevertheless, the precise role of ZNF692 in pan cancer remains uncertain." (PMID 37980166, 2023). "ZNF692 may mediate resistance to certain drugs in pan cancer." (PMID 37980166, 2023). "However, the expression of ZNF692 in the context of pan cancer remains unknown." (PMID 37980166, 2023). "For example, ZNF692 may be involved in activating pathways such as Wnt/ beta-catenin, Notch, or Hedgehog, which play a key role in the EMT process and self-renewal of cancer stem cells." (PMID 38291502, 2024). "By affecting these signaling pathways, ZNF692 may not only promote EMT, but also the maintenance and proliferation of cancer stem cells, which is critical for tumor persistence and resistance to treatment." (PMID 38291502, 2024). "Additionally, we observed a correlation between ZNF692 expression and MSI in eight cancer types, as well as with TMB in ten cancer types." (PMID 37980166, 2023). "Zinc finger protein 692 (ZNF692), a kind of Krüppel C2H2 zinc finger transcription factor, exhibited abnormal expression in different types of malignancies and showed a correlation with the clinical prognosis of patients as well as the aggressive characteristics of cancer cells." (PMID 38650011, 2024).
tumor (8 papers, 2020 to 2025). "Analysis with TCGA datasets showed that ZNF692 was expressed higher in tumor tissues, and its high expression was associated with low survival rate." (PMID 40391655, 2025). "ZNF692 exhibited promising diagnostic potential in certain tumor types." (PMID 37980166, 2023). "The tumor volume and weight of the sh-ZNF692 and sh-ALDOA groups were significantly lower than those of the control group (P < 0.05)." (PMID 38453820, 2024). "ZNF692, located on chromosome 1q44, is a key transcription factor that binds to the promoter regions of key genes regulating tumor progression." (PMID 38735008, 2024). "In this study, we found that ZNF692 was significantly upregulated in tumor tissues compared with adjacent normal tissues, with stage 2, 3, and 4 tissues having higher ZNF692 expression levels than stage 1 tissues." (PMID 38735008, 2024). "Consistent with the mRNA expression data, the IHC results showed that the expression of ZNF692 was higher in tumor tissues than in paracancerous tissues." (PMID 38735008, 2024). "Because most of our samples (41/58) were TNM stage 2 tissues, the effect of ZNF692 on tumor stage needs further analysis using a large sample size." (PMID 38735008, 2024). "The qRT-PCR findings indicated that the mRNA levels of ZNF692 and TNK2 were reduced in the tumor formed by cells with suppressed ZNF692 compared to the tumors induced by control cells." (PMID 38650011, 2024). "UMAP clustering showed that tumor program 1 (TP1) tumor cells were the dominant cells expressing ZNF692 and were responders to ICB therapy." (PMID 38735008, 2024). "The expression of ZNF692 mRNA was significantly higher in the ccRCC tumor tissues than in the paired adjacent normal tissues (p < 0.001)." (PMID 38735008, 2024). "The results indicate that ZNF692 holds promise as a potential biomarker for tumor diagnosis, prognosis, and immunotherapeutic interventions." (PMID 37980166, 2023). "In addition, the expression of ZNF692 in tumor program 1 (TP1) tumor-like cells dramatically changed after patients received ICB therapy, with loss of ZNF692 expression in TP1 cells." (PMID 38735008, 2024). "A xenograft mouse model was established to evaluate the effect of ZNF692 on tumor growth in vivo." (PMID 38650011, 2024). "Furthermore, the immunohistochemistry (IHC) findings demonstrated a reduced proportion of Ki-67-positive cells in the tumor that had undergone stable knockdown of ZNF692, compared to the control tumors." (PMID 38650011, 2024). "Collectively, these data suggest that tumor cells with high ZNF692 expression may be the primary responders to ICB therapy, but further experimental and clinical verification is needed." (PMID 38735008, 2024). "However, upon exposure to immune checkpoint blockade (ICB) agents, a portion of ZNF692-positive tumor cells (referred to as tumor program 1 cluster (TP1) cells) in advanced ccRCC patients responded to ICB therapy." (PMID 38735008, 2024). "Our results suggests that ZNF692 may govern immune homeostasis in the tumor microenvironment of ccRCC." (PMID 38735008, 2024). "However, the expression pattern of ZNF692 in tumor-like cells was dramatically altered after ICB therapy." (PMID 38735008, 2024). "Compared with the control group, the sh-ZNF692 and sh-ALDOA groups showed lower tumor growth rates (P < 0.05)." (PMID 38453820, 2024). "To investigate the role of ZNF692 in ccRCC, we analyzed expression profiles using the TCGA KIRC dataset of RNA-seq data for paired tumor and adjacent normal tissues." (PMID 38735008, 2024). "Therefore, ZNF692 may regulate ALDOA in HCC by modulating KAT5-mediated acetylation, thereby promoting glycolysis and tumor growth." (PMID 38453820, 2024).
ZNF692 also shares sentences with these, for which no sentence is quoted: clear cell renal carcinoma (2 papers); breast carcinoma (1); colon cancer (1); colorectal cancer (1); leukemia (1); melanoma (1); renal carcinoma (1); Wilms tumor (1).